RAB11A (RAB11A, member RAS oncogene family)
Diseases named in the same sentence as RAB11A in open-access papers (continued):
Sharing a sentence is not in itself a finding about the gene and the disease.
lung carcinoma (6 papers, 2017 to 2024). "Other proteins with TBC1 domain also function in cancer; for instance, TBC1 domain family member 23 can interact with Ras-related protein Rab-11A to promote poor prognosis in lung cancer." (PMID 35321246, 2022). "Rab11a is overexpressed in lung cancer and promotes cancer proliferation through regulation of Hippo signaling." (PMID 33178272, 2020). "Other studies further suggest that Rab11A has an oncogenic role in several cancers including colorectal, pancreatic, breast, and lung cancers." (PMID 29954076, 2018). "As for lung cancer tissues, 46.72% (57/122) cases showed high cytoplasmic Rab11a staining(final score ≥ 4) (Figure 1A2 and 1A3) and the rest showed low Rab11a staining." (PMID 28468127, 2017). "Relative expression level of Rab11a was analyzed by western blot in a panel of lung cancer cell lines." (PMID 28468127, 2017). "We also examined Rab11a protein in 8 cases of fresh lung cancer tissues with their corresponding normal tissue." (PMID 28468127, 2017). "Together, these results suggested that Rab11a regulates lung cancer progression through, at least partly, regulation of YAP and inhibition of Hippo signaling pathway." (PMID 28468127, 2017). "Taken together, our observations demonstrate that Rab11a regulate lung cancer aggressiveness through regulation YAP and Hippo signaling pathway." (PMID 28468127, 2017). "Accordingly, Rab11a levels in lung cancer cell lines were higher than that in normal bronchial cell line HBE." (PMID 28468127, 2017). "In this study, we were able to show that Rab11a overexpression facilitated lung cancer cell growth and invasion." (PMID 28468127, 2017). "Rab11a promotes proliferation and invasion in lung cancer and pancreatic cancer." (PMID 33178272, 2020). "Interestingly, Rab11a promotes YAP nuclear transport in lung carcinoma cells, alluding to a potential intersection between E6/E7-mediated YAP nuclear import and Rab11a to stimulate cell proliferation." (PMID 31475144, 2019). "In lung cancer, high Rab11A levels correlate with advanced stage and poor survival." (PMID 29954076, 2018). "To test whether Rab11a could regulate Hippo signaling, we transfection lung cancer cells with Rab11a plasmid and siRNA, together the with TEAD reporter plasmid which reflect activation of YAP target genes transcription." (PMID 28468127, 2017). "Rab11a expression in lung cancer specimens may be a valuable biomarker for aggressive behavior and poor prognosis." (PMID 28468127, 2017). "In conclusion, this study delineates the functional role of Rab11a in lung cancer progression." (PMID 28468127, 2017). "Furthermore, immunoprecipitation showed that Rab11a interacted with YAP in lung cancer cells." (PMID 28468127, 2017). "In addition, Rab11a upregulated lung cancer growth through YAP protein." (PMID 28468127, 2017). "In YAP-siRNA treated lung cancer cells, the Rab11a siRNA induced change of CTGF and cell cycle proteins was not significant." (PMID 28468127, 2017). "To determine whether Rab11a is involved in the regulation of Hippo signaling in lung cancer cells, we examined the level of YAP and its nuclear localization in Rab11a transfected and depleted cells." (PMID 28468127, 2017).
ovarian carcinoma (6 papers, 2021 to 2024). A malignant neoplasm originating from the surface ovarian epithelium. "This generated a robust catalogue of Rab4a-, Rab11a- and Rab25-associated proteins within migratory A2780 ovarian cancer cells, providing an important resource for further understanding of how trafficking networks perform their myriad functions, including in cell migration." (PMID 37232246, 2023). "Here, we used BioID-based proximity labelling to characterise the protein complexes that form around recycling vesicles in a mesenchymal, migratory, ovarian cancer cell line model, specifically focusing on Rab4a, Rab11a and Rab25." (PMID 37232246, 2023). "FACS and fluorescence widefield images (background subtracted) of mNeonGreen or mCherry knock-ins to Rab11a or Rab11b loci of (D) A2780 or (E) COV362 ovarian cancer cell lines." (PMID 35708998, 2022). "Rab11a, Rab11b, and Rab25 were significantly enriched in ovarian cancer, both for primary and recurrent tumors." (PMID 35708998, 2022). "A2780 ovarian cancer cells show abundant Rab11a/b expression while the more restricted family member Rab25 is not expressed." (PMID 35708998, 2022). "For further work, we selected a commonly used cell line model for ovarian cancer, A2780, and knocked-in mNeonGreen or mCherry after the start codon of Rab11a or Rab11b, respectively." (PMID 35708998, 2022). "Similarly, several Rab11a/Rab11b/Rab25 splicing isoforms are enriched in ovarian cancer compared to normal tissue." (PMID 35708998, 2022). "Furthermore, our results suggest that although Rab11b and Rab11a may have a complementary function in migration and invasion of A2780 ovarian cancer cells, they differ substantially in their post-transcriptional regulation." (PMID 35708998, 2022). "Of the three proteins investigated (RAB4A, RAB5A, and RAB11A), only RAB5 expression was found to correlate with T-DM1 toxicity in a cell line panel of HER2-positive breast and ovarian cancer." (PMID 34741021, 2021).
pancreatic cancer (5 papers, 2020 to 2025). "Here, we show that benproperine phosphate (BPP), a cough suppressant, triggers AMPK/mTOR‐mediated autophagy initiation and disturbs Ras‐related protein Rab‐11A (RAB11A)‐mediated autophagosome–lysosome fusion, resulting in excessive accumulation of autophagosomes in pancreatic cancer (PC) cells." (PMID 33226737, 2021). "Rab11a also activates Wnt/β-catenin signaling to enhance cancer progression in pancreatic cancers." (PMID 33178272, 2020).
cervical carcinoma (4 papers, 2019 to 2025). A carcinoma arising from either the exocervical squamous epithelium or the endocervical glandular epithelium. "The most active inhibitors disrupted Rab11A prenylation in the human cervical carcinoma HeLa cell line." (PMID 33490034, 2020). "We tested whether these two glycolytic enzymes are elevated in Rab11a-exosome-enriched sEV preparations generated from another cell type, which undergoes a Rab11a-exosome switch in glutamine-depleted conditions, human HeLa cervical cancer cells." (PMID 40676215, 2025). "Culturing HeLa cervical cancer cells in glutamine‐depleted medium, which reduced phosphorylation of S6 and 4E‐BP1, slightly increased EV number (A′, and A′′′, Fig EV4E) and increased Rab11a secretion relative to other exosome markers (and S7A′′), while cellular levels of Rab11a were unaffected." (PMID 32720716, 2020).
influenza (4 papers, 2017 to 2021). An acute viral infection of the respiratory tract, occurring in isolated cases, in epidemics, or in pandemics; it is caused by serologically different strains of viruses (influenzaviruses) designated A, B, and C, has a 3-day incubation period, and usually lasts for 3 to 10 days. "Rab11A RE have been implicated in the cytoplasmic transport of influenza vRNA segments to the plasma membrane for packaging and budding (12, –, 14)." (PMID 28724771, 2017). "Defining the intracellular location of Rab11A and influenza vRNP association." (PMID 28724771, 2017). "To test this hypothesis, we visualized Rab11a, F-Actin and viral nucleoprotein [NP]—as a marker for vRNPs—in MDCK cells infected with either influenza A/Netherlands/602/2009 [NL09; pH1N1] or A/Panama/2007/99 [P99; H3N2] virus." (PMID 34473799, 2021).
pituitary tumor (4 papers, 2019 to 2022). A benign or malignant neoplasm affecting the pituitary gland. "LncRNA SNHG1 activated the TGFBR2/SMAD3 and RAB11A/Wnt/β-catenin pathways to promote the progression of pituitary tumors by sponging miR-302/372/373/520 in pituitary tumor cells." (PMID 32192168, 2020). "The results showed that RAB11A was upregulated in invasive pituitary tumor tissues." (PMID 35432529, 2022). "For example, the SNHG1 lncRNA sequestered miR-302/372/373/520 and consequently activated TGFBR2 and RAB11A in invasive pituitary tumors, while DANCR acted as a decoy for miR-335-5p and miR-1972, thus promoting ROCK1-associated proliferation and metastasis in osteosarcomas." (PMID 30774556, 2019). "Moreover, RAB11A was upregulated by lncRNA SNHG1 and activated the WNT/β-catenin pathway in invasive pituitary tumors." (PMID 33292272, 2020).
cystinosis (3 papers, 2015 to 2022). Cystinosis is a metabolic disease characterized by an accumulation of cystine inside the lysosomes, causing damage in different organs and tissues, particularly in the kidneys and eyes. "Finally, we found that LAMP2A localizes to Rab11a-positive vesicles in Ctns−/− cells but not in wild-type cells (Fig6C) further supporting possible alternative trafficking mechanisms for LAMP2A in cystinosis." (PMID 25586965, 2015).
epilepsy (3 papers, 2023 to 2025). A brain disorder characterized by episodes of abnormally increased neuronal discharge resulting in transient episodes of sensory or motor neurological dysfunction, or psychic dysfunction. "In conclusion, our results corroborated that Rab11a-dependent recycling of Glut3 inhibited seizure-induced neuronal disulfidptosis by alleviating glucose deficiency, which may be a novel target for the treatment of epilepsy and neuroprotective strategies in the future." (PMID 40437641, 2025). "The proband’s phenotype aligns with previous reports, where RAB11A-related NDDs were shown to affect gait, muscle tone, brain anatomy and physiology, vision, adrenarche, and body weight and structure, with some patients experiencing epilepsy." (PMID 40959816, 2025). "Our study revealed that Rab11a may be a target for treating epilepsy and protecting neurons." (PMID 40437641, 2025).
gastric cancer (3 papers, 2020 to 2025). A primary or metastatic malignant neoplasm involving the stomach. "Our current study demonstrated that Rab11a protein was elevated in gastric cancers and correlated with nodal metastasis, higher TNM stage, and local invasion." (PMID 33178272, 2020). "To address these questions, we evaluated Rab11a protein in gastric cancer tissues and analyzed its clinical significance." (PMID 33178272, 2020). "We first analyzed expression pattern of Rab11a in 108 cases of paraffin embedded gastric cancer tissues and 10 cases of normal gastric tissues using immunohistochemistry." (PMID 33178272, 2020). "Weak/negative staining of Rab11a was found in normal tissues while increased Rab11a staining was found in the cytoplasm of gastric cancer tissues." (PMID 33178272, 2020). "In conclusion, the current study identified novel roles of Rab11a as oncoprotein overexpressed in human gastric cancers." (PMID 33178272, 2020). "We found that Rab11a overexpression decreased cisplatin sensitivity and reduced cisplatin-induced apoptosis in gastric cancer cells." (PMID 33178272, 2020). "Rab11a protein expression was also examined in 10 pairs of fresh gastric cancer tissues with their adjacent normal tissues using western blotting." (PMID 33178272, 2020). "Rab11a promoted gastric cancer proliferation, invasion, and cisplatin resistance and prevented loss of mitochondrial membrane potential possibly through FAK/AKT signaling." (PMID 33178272, 2020). "We used different concentration of cisplatin (0.1, 0.5, 2.5, 5, and 10 μg/mL) to treat gastric cancer cells with Rab11a overexpression and depletion and checked the inhibition rate of cisplatin on cell viability using MTT assays." (PMID 33178272, 2020). "In the current study, we examined Rab11a protein expression and found it was upregulated in 49 of 108 gastric cancer tissues and correlated with local invasion, nodal metastasis, and advanced stage." (PMID 33178272, 2020). "It has been reported that RAB11A facilitates gastric cancer progression and metastasis." (PMID 36760469, 2023). "Besides, RAB11A is up-regulated in human gastric cancer cells and facilitates the proliferation and invasion of cancer cells through the FAK/AKT pathway." (PMID 36760469, 2023). "RAB11A is overexpressed in diverse types of human cancers, such as lung and gastric cancer." (PMID 36760469, 2023). "Accordingly, Rab11a could positively regulate cyclin D1 protein, suggesting Rab11a accelerated gastric cancer growth through induction of cell cycle regulators." (PMID 33178272, 2020). "In summary, our data demonstrated that Rab11a is upregulated in human gastric cancers." (PMID 33178272, 2020). "In addition, we profiled Rab11a protein in a panel of gastric cancer cell lines and normal GES-1 cell line." (PMID 33178272, 2020). "Rab11a protein was higher in gastric cancer cell lines than normal gastric cell line." (PMID 33178272, 2020). "To validate their relationship in gastric cancer cells, we used FAK inhibitor to block its function and the effects of Rab11a on cyclin D1, MMP2, and Bcl-2 were significantly reduced." (PMID 33178272, 2020).
hepatocellular carcinoma (3 papers, 2020 to 2023). A malignant tumor that arises from hepatocytes. "Rab11 upregulates MMP2 and activates AKT signaling in hepatocellular carcinoma, suggesting the function of Rab11a might share some similarities." (PMID 33178272, 2020).
non-small cell lung carcinoma (3 papers, 2017 to 2020). A group of at least three distinct histological types of lung cancer, including non-small cell squamous cell carcinoma, adenocarcinoma, and large cell carcinoma. "Rab11A promotes non-small cell lung cancer (NSCLC) cell aggressiveness in vitro and tumor growth in vivo through upregulation of YAP." (PMID 29954076, 2018). "We also revealed that Rab11a inhibits Hippo signaling and promotes non-small cell lung cancer cell proliferation and invasion through regulation of YAP." (PMID 28468127, 2017). "To data, there was no report concerning protein expression pattern and clinical significance of Rab11a in human non-small cell lung cancer." (PMID 28468127, 2017).
Obesity (3 papers, 2024 to 2026). Accumulation of substantial excess body fat. "The differential expression of ribosomal proteins RPL30 and RAB11A following epicatechin supplementation holds significant physiological implications, particularly in obesity and metabolic regulation." (PMID 41104591, 2026). "The reduction in RAB11A could suggest a potential anti‐inflammatory effect of epicatechin supplementation, which may help attenuate the inflammatory environment often seen in obesity, thereby improving metabolic outcomes." (PMID 41104591, 2026).
osteosarcoma (3 papers, 2019 to 2023). A usually aggressive malignant bone-forming mesenchymal neoplasm, predominantly affecting adolescents and young adults. "In this study, RAB11A and RAB5A were also identified as the hub nodes of osteosarcoma." (PMID 36438897, 2022).
Sepsis (3 papers, 2017 to 2024). Sepsis is defined as life-threatening organ dysfunction caused by a dysregulated host response to infection. "Rab11a deficiency in macrophages prevents sepsis-induced NLRP3 inflammasome activation and inflammatory lung Injury in mice." (PMID 37158595, 2023). "Silencing Rab11 and Rab11a was effective in preventing VE-cadherin recycling and markedly increased vascular permeability in an ALI model secondary to polymicrobial sepsis." (PMID 38533500, 2024).
brain inflammation (2 papers, 2022 to 2025). "oat-ELNs, targeting microglial cells, regulate the assembly of the HPCA/Rab11a/Dectin-1 complex, inhibiting alcohol-induced brain inflammation, and improving cognitive function." (PMID 40721664, 2025). "This coordinated assembling of the HPCA/Rab11a/dectin-1 complex by oral administration of oatN may contribute to the prevention of brain inflammation." (PMID 34897972, 2022).
Cerebral ischemia (2 papers, 2023 to 2025). Restriction of arterial blood supply to the brain associated with insufficient oxygenation to support the metabolic requirements of the tissue.
cholestasis (2 papers, 2018 to 2021). Impairment of the bile flow caused by obstruction within the liver, or outside the liver in the bile duct system. "The cholestasis results from the impairment of the MYO5B/RAB11A apical recycling endosome pathway in hepatocytes, the altered targeting of BSEP to the canalicular membrane and the increased ileal bile acid absorption." (PMID 30364420, 2018). "Together, these results suggest that the mechanism via which MYO5B variants cause cholestasis may not reflect a loss-of-function of myosin Vb, but a gain-of-toxic function of the mutant myosin Vb protein on active RAB11A at the interface of the trans-Golgi network and ARE." (PMID 33557414, 2021).
colon carcinoma (2 papers, 2014 to 2021). "Previously, we demonstrated that loss of Rab11a in the human, mouse, and fly gut epithelium leads to hyperproliferation, increased tumorigenic activity, and progression of colon cancer." (PMID 34058200, 2021).
diabetes (2 papers, 2021 to 2022). "As well, STZ-induced diabetes did not alter the pattern of distribution between Rab11A and glucagon, but did decrease the colocalization between insulin and Rab11A." (PMID 34923907, 2022). "In contrast, insulin showed a strong colocalization with Rab11A (PCC 0.63 ± 0.09) or Rab11B (PCC 0.61 ± 0.06), which significantly decreased (p < .001) following induction of diabetes (colocalization of insulin with Rab11A, PCC 0.35 ± 0.5, or Rab11B, PCC 0.38 ± 0.07)." (PMID 34923907, 2022).
encephalopathies (2 papers, 2018 to 2023). "Rab11A and Rab11B are mutated in developmental disorders, leading to encephalopathies and co-occurrence of seizures and intellectual disability." (PMID 30217979, 2018).
intellectual disabilities (2 papers, 2018 to 2023). "We here report a novel DNM RAB11A variant, NM_004663.5: c.98G > C (NP_004654.1: p.(R33P)), identified in a boy with severe intellectual disability (ID) and hypomyelination." (PMID 40225156, 2023). "Whole exome sequencing/whole genome sequencing has accelerated the identification of novel genes associated with intellectual disabilities (ID), and RAB11A which encodes an endosomal small GTPase is among them." (PMID 40225156, 2023). "Both Rab11A and Rab11B are mutated in developmental disorders, with putative inactivating Rab11A or Rab11B mutations leading to intellectual disability and brain malformation." (PMID 30217979, 2018).
leukemia (2 papers, 2021 to 2023). A malignant (clonal) hematologic disorder, involving hematopoietic stem cells and characterized by the presence of primitive or atypical myeloid or lymphoid cells in the bone marrow and the blood. "In fact, we successfully downregulated Rab11A via AuNPs functionalized with an anti-RAB11A hairpin in the leukemia K562 cells, attaining a staggering 40% decrease of mRNA expression after 6 h incubation, which endure up to 24 h." (PMID 36986603, 2023).
microcephaly (2 papers, 2021 to 2025). A congenital or acquired developmental disorder in which the circumference of the head is smaller than normal for the person's age and sex. "For all the reported 17 children with RAB11A mutations, we noticed that five children with microcephaly experienced a series of OFC measurements." (PMID 40959816, 2025).
microvillus inclusion disease (2 papers, 2015). Microvillus inclusion disease (MVID) is a very rare, severe, malabsorbative syndrome characterized clinically by protracted or intractable neonatal secretory diarrhea and histologically by inclusion bodies on the intestinal epithelium. "Mutations in MYO5B encoding Myosin 5b, which acts as a molecular motor not only for Rab11a, but also Rab11b, Rab25, and Rab8, cause MicroVillus Inclusion Disease (MVID) in which malabsorption results from the absence of the intestinal brush border." (PMID 26116792, 2015).